ABCG2 (ATP binding cassette subfamily G member 2 (JR blood group))
Diseases named in the same sentence as ABCG2 in open-access papers (continued):
Sharing a sentence is not in itself a finding about the gene and the disease.
tumor (continued). "Collectively, these findings indicate ABCG2 as a key mediator of chemoresistance in tumor cells." (PMID 41541684, 2026). "Importantly, tumor tissue obtained at progression after BL-B01D1 treatment confirmed ABCG2 upregulation, validating a clinically relevant resistance mechanism." (PMID 41945392, 2026). "In our study, drug-insensitive tumor cell lines exhibited high ABCG2 expression." (PMID 41541684, 2026). "The finding that the fraction of ABCG2-positive was higher in resected specimens than in biopsies but similar in primary tumors and metastases, suggests that size of tumor area assessed may impact results." (PMID 40548120, 2025). "Interestingly, ABCG2 expression has been closely associated with key aspects of HCC progression, including tumor initiation, cell proliferation, metastasis, and the development of chemoresistance." (PMID 40830621, 2025). "ABCG2 is a marker protein of tumor stem cells and drug efflux transporter protein." (PMID 40370575, 2025). "Another factor that may influence intratumoral TS levels is the expression of drug efflux transporters, such as ABCG2, which actively exports porphyrin-based photosensitizers from tumor cells, thereby lowering intracellular drug concentrations." (PMID 40284018, 2025). "Similarly, cabozantinib potentiated the cytotoxic and anti-tumor effects of topotecan, a well-known substrate for ABCG2, in chemoresistant NSCLC cells in vitro and xenograft models, as well." (PMID 41154409, 2025). "The ABCB1 and ABCG2 drug efflux transporters can also be expressed in tumor cells themselves." (PMID 40893689, 2025). "Although ABCG2 is higher in GBM6R, available data suggest it is unlikely to explain the phenotype: in GBM cells ABCB1 dominates intracellular TMZ efflux, while ABCB1/ABCG2 chiefly restrict brain entry at the BBB—an exposure effect that cannot account for within-tumor GBM6 vs GBM6R differences." (PMID 41271669, 2025). "Finally, we examined the expression of the stemness marker OCT4 and the drug resistance marker ABCG2 after the treatment of tumor spheres with all these combinations of drugs and irradiation." (PMID 40647457, 2025). "Also, silencing FOXP1 and inhibiting ABCG2 in orthotopic mouse models led to significant reductions in tumor sizes, highlighting the clinical potential of therapeutics against FOXP1." (PMID 40169859, 2025). "However, several studies have suggested that ABCG2 can promote tumor survival via MDR-independent mechanisms." (PMID 38641063, 2024). "Targeting ABCG2 could enhance chemoradiotherapy efficacy and improve patient outcomes, which highlights its value in assessing tumor aggressiveness and designing treatment strategies." (PMID 38542090, 2024). "Previous studies have associated ABCG2 and KLF4 with tumor stemness, suggesting that these genes may serve as representative markers and potentially reflect the disparity in tumor stemness between cell types." (PMID 39389944, 2024). "ABCG2 is also a well-recognized transporter involved in MDR across various tumor types." (PMID 39403600, 2024). "This strategy may significantly reduce tumor size, especially in ABCG2-positive tumors in the first-line setting." (PMID 39033209, 2024). "This has led to speculation that ABCG2 has an additional function(s) that promotes tumor cell survival under stressful conditions." (PMID 38641063, 2024). "The enforced expression of Cirbp alone had little impact on the expression of stem cell-related markers (i.e., Nanog and Bmi-1) or slightly upregulated the expression of Sox2, Oct4 and ABCG2 in whole xenograft tumor lysates from CNE2 cells, as compared to those of control group (i.e., LV-con group)." (PMID 38419081, 2024). "The expression levels of PMI and ABCG2 in tumor tissues were determined using immunohistochemistry." (PMID 38576495, 2024). "To further define the mechanism(s) by which ABCG2 enhances tumor cell survival, we considered the possibility that ABCG2 might accomplish this through interaction with other membrane proteins." (PMID 38641063, 2024).
tumor (continued). "However, several studies have shown that ABCG2 can also confer an MDR-independent survival advantage to tumor cells exposed to stress." (PMID 38641063, 2024). "This senescence-associated stemness enhances the tumour’s aggressiveness and risk of recurrence, as demonstrated in liver cancer studies where EpCAM+/CD133+ stem cells exhibit increased resistance to doxorubicin due to elevated ABCG2 expression." (PMID 39679367, 2024). "However, the fraction of these cells is so small that it should not significantly influence the results of the assessment of the ABCG2 mRNA level in tumor tissue." (PMID 39457707, 2024). "Furthermore, Western blotting confirmed lower expression of oncogenic markers, stemness markers, CAF markers (α-SMA), and PROX1 as well as lower expression of ABCG2 in the PROX1-knockdown tumor samples as compared with vector control." (PMID 38244581, 2024). "Interestingly, the cisplatin++ group mirrored the cisplatin+ group by exhibiting an increase in EpCAM+/ABCG2+/pimonidazole+ CTCs between the 2nd and 8th week of tumor growth." (PMID 39963656, 2024). "Likewise, the AF detected was ABCG2-mediated, as simultaneous treatment of all tumor digestions with riboflavin and FTC reduced the appearance of AF cells, confirming that the AF detected in all tumors is identical to that described previously." (PMID 39225547, 2024). "However, SP heterogeneity complicates interpretation, with ABCG2 identifying fast‐cycling tumor progenitors while ABCG2‐negative cells possess primitive stem‐like characteristics." (PMID 39309691, 2024). "While this observation defines a new mechanism by which ABCG2 may impact tumor cell survival, how this is accomplished and whether other mechanisms are also in play have not yet been determined." (PMID 38641063, 2024). "New MDR modulators such as tazemetostat, an I-CBP112-CBP/EP300 bromodomain inhibitor, or sonidegib may increase the tumor cells’ sensitivity to anticancer agents by the functional inhibition of ABCG2." (PMID 39457707, 2024). "Furthermore, to determine the value of the ABCG2 profile and the percentage of ABCG2-positive tumor cells in predicting potential complications, a ROC analysis was performed." (PMID 38542090, 2024). "First, ABCG2 protects cells against compounds initiating and/or intensifying neoplasia." (PMID 37445716, 2023). "In addition, the expression of ABCG2 in tumor tissues, especially in the so-called tumor stem cells or drug-tolerant persister cells, correlates with an unfavorable prognosis of tumor chemotherapy." (PMID 36763413, 2023). "Additionally, ABCG2 expression was compared between normal colon tissue, primary tumour and metastatic tissue." (PMID 37445716, 2023). "Moreover, our data indicated that membrane transporters OATP2B1 and ABCG2, which regulated by β-catenin signaling pathway, mediated tumor-specific accumulation and retention of MHI-148 in HCC cells." (PMID 37064109, 2023). "Complementary to this, some tumor cells may also express other efflux transporters responsible for drug resistance, such as ABCG2 (breast cancer resistance protein, BCRP) or ABCC1 (multidrug-resistance-associated protein 1, MRP1)." (PMID 36836823, 2023). "However, the metastatic tissue showed higher ABCG2 expression than the primary tumour tissue (p = 8.37 × 10−15)." (PMID 37445716, 2023). "Moreover, our study provides the supporting evidence that the membrane transporters of OATP2B1 and ABCG2 regulated by β-catenin signaling pathway mediate tumor-specific accumulation and retention of MHI-148 in HCC cell." (PMID 37064109, 2023). "Additionally, PepO treatment also resulted in a decrease in the tumor stem cell-related proteins ABCG2, OCT4, SOX2 and Olig2." (PMID 37925462, 2023).
tumor (continued). "Moreover, several candidate genes, such as VWA5A, ABCG2, A2M and IGSF1, associated with tumor suppression, growth and age were expanded, implicating their potential roles in the exceptional longevity of turtles." (PMID 37508370, 2023). "Whether the primary tumor–derived EpCAM+/ABCG2- CSCs exhibit BCG-induced PIBA requires further investigation." (PMID 36248858, 2022). "For testis, tumor tissue revealed a higher ABCG2 expression compared to the normal tissue." (PMID 36555598, 2022). "Downregulation ABCG2 might promote tumor progression and contribute to the aggressive growth of CHOL." (PMID 36158120, 2022). "Recent studies have shown that PTEN gain of function could prevent ABCG2 activity with respect to tumor stem cell characteristics." (PMID 36613808, 2022). "By contrast, we can see from the results of evaluating the stromal and immune scores in KIRC samples, ABCG2 expression significantly shows an opposite tendency, suggesting that ABCG2 plays a role in the KIRC tumor microenvironment and can be used as a therapeutic target to aid drug sensitivity." (PMID 36555598, 2022). "Importantly, the death signal–rich CM exert significant toxicity to EPCAM+ABCG2+ CSCs residing in the hypoxic niche of tumor xenografts." (PMID 36248858, 2022). "Its co-localization with ABCG2 in squamous cells in the parenchyma invaded by the tumor formation allows us to hypothesize p75NTR and p75ICD roles in tumor invasion and CSC spreading in LSCC patients." (PMID 35681602, 2022). "Furthermore, most of our work has been performed in vitro, using hypoxia/oxidative stress–enhanced side-population cells or EPCAM+/ABCG2+ cells of established tumor cell lines." (PMID 36248858, 2022). "The TME can both directly and indirectly affect the ability of circRNAs to regulate tumor drug resistance; for example, the inflammatory factor IL-7 can reduce the expression of ABCG2 (ATP-binding cassette family protein) and regulate cisplatin resistance in NSCLC." (PMID 35615158, 2022). "Moreover, the results of qRT‐PCR and Western blot demonstrated a decline in the expression of MDR1, MRP, LRP and ABCG2 in tumour tissues of mice treated with Erlotinib, the effect of which was abolished by HCC827R‐CSC‐EVs." (PMID 35605028, 2022). "Furthermore, we investigated the genetic alteration status of ABCG2 in the different tumor samples of the TCGA cohorts." (PMID 36555598, 2022). "Apart from the tumor cells, the tumor tissues in the TCGA database also consist of other cell types, such as stromal and immune cells, which means that tumor purity could be a potential influencing factor on ABCG2 expression and the stemness scores." (PMID 36555598, 2022). "Our future work will focus on determining whether this therapeutic enhancement approach leads to enhanced ALA-PpIX fluorescence and PDT response in tumor models with elevated ABCG2 activity." (PMID 34545713, 2021). "Finally, the mouse tumor xenograft model was established and the tumor volume and weight were measured, and ABCG2 expression was conducted by immunohistochemistry assay." (PMID 34454479, 2021). "Moreover, the oral administration of 30 mg/kg of VKNG-1 with irinotecan (10 mg/kg i.p.)remarkably attenuated the tumor growth in mice implanted with ABCG2 overexpressing S1-M1-80 mouse xenografts." (PMID 34572902, 2021).
tumor (continued). "Intra-tumor heterogenicity in the implanted tumors and tumor–host interactions, such as the interplay between the tumors and their micro-environment, may be a factor contributing to the ABCG2-independent MDR observed in NCI-H460/TPT10 xenograft models." (PMID 33829017, 2021). "The de-functional ABCG2 rs2231142, on one hand, could maintain accumulation of chemotherapeutic compounds, which would achieve reduced tumor burden." (PMID 33531973, 2021). "Previous studies showed overexpression of ABCG2 in a variety of tumor tissues, which could potentially indicate the probability of chemotherapy resistance." (PMID 33509236, 2021). "In addition, VKNG-1 enhanced the anticancer efficacy of irinotecan in ABCG2- overexpressing mouse tumor xenografts." (PMID 34572902, 2021). "The ABCG2 expression was analyzed in the tumor tissues and adjacent normal tissues of 68 patients." (PMID 33509236, 2021). "The mRNA expression of ABCG2 in tumor tissues was analyzed for each patient." (PMID 33509236, 2021). "Since estrogen can regulate the expression of ABCG2 in tumor cells, we wondered whether estrogen can increase the excretion of urate by regulating the expression of ABCG2 and thereby exert an antihyperuricemic effect." (PMID 34144706, 2021). "If our results can be translated to humans, it suggests that combining MLN7243 with ABCG2 inhibitors may enhance the anticancer efficacy for patients with high tumor ABCG2 level." (PMID 34336849, 2021). "ABCG2 was obviously highly expressed in the tumor tissues than in the normal tissues (p < 0.001)." (PMID 33509236, 2021). "Notably, an increased level of the tumor suppressor, miR-142-3p, whose targets include LGR5, IL-6, and ABCG2, was detected in association with MSI-N1014 treatment." (PMID 32560222, 2020). "However, the animal body weight of the animals was significantly decreased by the EC16-1/saporin treatment compared with day 1, in the ABCG2 tumor xenograft models." (PMID 32098067, 2020). "Three distinguishable ABCG2 expression patterns of the tumor cells could be detected, namely basolateral membrane, apical membrane and cytoplasmic immunostaining." (PMID 32708825, 2020). "However, other studies comparing the expression of ABCG2 mRNA in normal colon tissue and tumor tissue showed a decreased expression in tumor tissue." (PMID 33261018, 2020). "Remarkably, ABCG2, although resembling more closely an importer, is the hallmark MDR exporter able to handle hundreds of xenobiotic compounds in physiological detoxification, as well as many anticancer drugs in tumor therapy." (PMID 33169382, 2020). "In addition, CD117 is overexpressed in OCSCs and mediates both tumor-initiating capacity and chemoresistance to cisplatin/paclitaxel by activating the Wnt/β-catenin-ABCG2 axis." (PMID 32512891, 2020). "Our data were consistent with the assumption of tumor repopulation due to differentiation of CSCs and may point to a role of ABCG2 in autophagy regulation in these progenitor cells." (PMID 32397297, 2020). "However, this uptake is opposed by action of ABC membrane transporters, such as ABCB1, MRP1 (ABCC1), and ABCG2, which excrete the radiotracer into extracellular space of tumor cells." (PMID 32562004, 2020). "Based on our previous studies, and data published by others, we raised the hypothesis that mCRC patients having low basolateral membrane ABCG2 immunoreactivity in their tumor cells benefit the most from irinotecan containing therapy." (PMID 32708825, 2020). "In addition, quantitative targeted absolute proteomics (QTAP) was applied to determine ABCB1 and ABCG2 levels in surgically resected tumor tissue." (PMID 31832814, 2019). "In vivo results also confirmed that IL-7 only in combination with DDP could remarkably induce tumor regression with reduced levels of ABCG2 in tumorous tissues." (PMID 31915416, 2019).
tumor (continued). "Recently, we found that gefitinib inhibits both ABCB1 and ABCG2, and that the antitumor activity, tumor tissue, and blood concentrations of SN-38 (the active metabolite of irinotecan) are increased in tumor-bearing mice by administration of gefitinib in combination with irinotecan." (PMID 31340525, 2019). "PI3K signals and the expression of ABCG2 were also analyzed in the tumor samples." (PMID 31915416, 2019). "It was confirmed that ABCG2 inhibitors would effectively increase the anti-tumor efficacy of purine nucleosides by blocking drug efflux which may be a significant of resistance when dCK levels are low22." (PMID 31575977, 2019). "In addition, ABCB1 and ABCG2 levels were determined in surgically resected tumor tissue of four patients using quantitative targeted absolute proteomics." (PMID 31832814, 2019). "In addition, miR-519c was found to be involved in the expression and regulation of genes related to chemotherapeutic sensitivity of tumor cells, such as ATP binding cassette subfamily G member 2 (ABCG2)." (PMID 31885571, 2019). "Colonies were cloned from the secondary cultures and analyzed by RT-PCR for mRNA expression of Gp78/AMFR, the tumor stem cell gene markers ABCG2 and Oct-4 and the thyroid differentiation markers thyroglobulin (TG) and thyroid stimulating hormone receptor (TsHR)." (PMID 31431834, 2019). "Even in the presence of a disrupted BBTB with fenestrated capillaries, endothelial cells may have sufficient ABCB1/ABCG2 transport capacity to limit tumor distribution of such drugs." (PMID 31832814, 2019). "ABCG2 inhibition could represent a chief strategy in this setting, contributing to the eradication of tumor-initiating CSCs." (PMID 31443516, 2019). "This suggested that tumor resistance related to overexpression of ABCG2 could possibly be overcome by administering EGFR TKIs in combination with anticancer agents that are ABCG2 substrates." (PMID 31340525, 2019). "Similarly, si-hVDAC1 treatment of A549-derived tumours greatly decreased the expression of ABCG2, SOX2, CD44, CD144, CD133, KLF4, Oct3/4, EPCAM and Nanog, also as evaluated by IHC, immunoblotting or q-RT-PCR." (PMID 30544833, 2018). "The basic principle of its tumor selectivity is considered not to be metabolism, but rather its affinity to albumin and its possible association with transporters such as ABCG2, resulting in its accumulation in lysosomes." (PMID 29441040, 2018). "On the other hand, the results showed a positive association between ABCG2 expression level and tumors stages (P= 0.025) and negative association between ABCG2 expression level and tumor size, lymph node, gender and /or patients' age." (PMID 31516883, 2018). "Using immunohistochemical analysis of the tumor sections, we determined that the expression of ABCG2 (drug resistance marker), β-catenin and WNT1 (stemness markers) were all significantly decreased in the combined treatment group while pro-apoptotic marker, Bax was increased." (PMID 30005681, 2018). "Therefore, the effect of ABCG2 single nucleotide polymorphism on ABCG2 function, pharmacokinetics and the mechanism of ABCG2 effect on tumor will be the focus of our future research." (PMID 30356705, 2018). "Next, we investigated the effect of CBP501 on ABCG2 expression in vivo in an Ex3ll tumor xenograft." (PMID 28969049, 2017). "In spite of these findings, the development of ABCG2 inhibitors is being expedited, because ABCG2 provides multidrug resistance for tumor cells by active drug efflux, thus the bioavailability of anticancer drugs can be improved by co-administration with ABCG2 inhibitors." (PMID 28270772, 2017). "Further investigation indicated that ABCG2 is over-expressed in various tumor cells." (PMID 28029654, 2017). "A, comparison of mRNA levels of ABCG2 between normal kidney tissue and tumor, p = <0.0001." (PMID 28347288, 2017). "The results strongly suggested a predictive role of tumor ABCG2 mRNA expression." (PMID 28880238, 2017).